ARG1 (arginase 1)
Diseases named in the same sentence as ARG1 in open-access papers (continued):
Sharing a sentence is not in itself a finding about the gene and the disease.
tumor (continued). "Notably, the production of ARG1 was highest in the CD206bright macrophages, confirming that CD206 expression is correlated with the immunosuppressive function of tumor-conditioned macrophages." (PMID 40588561, 2025). "In the tumor microenvironment (TME), TREM2+ macrophages display a transcriptional program enriched for immunosuppressive mediators such as IL-10, TGF-β, and arginase-1 (ARG1), and show reduced expression of antigen-presentation molecules (e.g., MHC-II)." (PMID 40821795, 2025). "Immunohistochemistry was significant for Ki-67 expression in 60% of tumor cells, positive staining for vimentin and P16, and negative staining for hepatocyte markers (arginase-1 and hepatocyte)." (PMID 40842593, 2025). "Immunohistochemistry played a pivotal role in differentiating UPS, as the tumor was negative for hepatocyte-specific markers (arginase-1 and hepatocyte) and positive for vimentin and P16, aligning with diagnostic criteria in the literature." (PMID 40842593, 2025). "We found that the expressions of PD-L1 and Arg-1 were increased in the TAM group and decreased in the TAM (αPD-L1) of the TAM+ NaB group, suggesting that the inhibition of PD-L1+ TAMs attenuated the tumor-promoting effects of TAMs." (PMID 41251471, 2025). "Taken together, both 1 and its glucoside 7 displayed particularly robust inhibitory effects against ARG1 mRNA expression and induced a significant increase in NOS2 mRNA expression, suggesting their capacity to alter the tumor-suppressive phenotype of RAW264.7 cells." (PMID 40430260, 2025). "Additionally, the PGE2 receptor 4 subtype (EP4) on MDSC membranes also binds to tumor cell‐expressed PGE2, a signaling pathway that promotes MDSC secretion of Arg1, thereby suppressing tumor immunity." (PMID 40452814, 2025). "Similarly, the amino acid arginine is depleted by the overexpression of arginase 1 (ARG1) in myeloid-derived suppressor cells (MDSCs) and some tumor cells." (PMID 41471036, 2025). "Similarly, although targeted inhibition of amino acid metabolism can reduce the release of immunosuppressive molecules such as ARG1, NO, and IDO1 in MDSCs and improve the tumor immunosuppressive microenvironment." (PMID 39990210, 2025). "Moreover, tumor cells can induce MDSC expansion in CRC, by secreting cytokines and other factors such as VEGF, iNOS, and ARG1, which reinforces immunosuppressive feedback loops." (PMID 41010517, 2025). "Additionally, cancer type-specific metabolic adaptations, such as Acod1 expression in breast cancer versus ARG1 in CRC, illustrate how neutrophils can vary in their functional roles based on the tumor context." (PMID 40387965, 2025). "The treatment of HCC mouse tumor tissues with B. thetaiotaomicron and acetic acid resulted in upregulated expression of CD86 and NOS2, along with downregulated expression of CD163 and ARG1, as demonstrated by real-time PCR data and flow cytometry data." (PMID 38270111, 2024). "In essence, arginase-1 acts as a competitor to nitric oxide synthase (NOS) for the limited pool of L-arginine, creating a microenvironment that starves CD8+ T cells of this essential amino acid and dampens their anti-tumor potential." (PMID 39450177, 2024). "Moreover, double IHC staining for Arginase-1 and ELTD1 showed that ELTD1-positive sinusoid-like vessels extended from Arginases-1-positive surrounding liver tissue into the tumor, allowing tumor cells to utilize vessel co-option to supply blood." (PMID 38960952, 2024). "MDSCs facilitate tumor invasion and metastasis, predominantly through factors like Indoleamine 2,3-dioxygenase (IDO), Arginase-1 (ARG1), Reactive Oxygen Species (ROS), IL-10, Inducible Nitric Oxide Synthase (iNOS), Cyclooxygenase-2 (COX-2), and Nitric Oxide (NO)." (PMID 38545114, 2024).
tumor (continued). "TANs have pro-tumor activity by producing ARG1, IL-10, TGF-β, and VEGF, and inhibiting cytotoxic T cells by expressing higher levels of immunosuppressive molecules, such as PD-L1, ARG1, and IDO, and lower of anti-tumor molecules, such as ROS and TNF-α." (PMID 39430759, 2024). "A next-generation sequencing transcriptomic immune profile analysis applied to 28 persistent CIN3 lesions and 14 normal biopsies identified four genes, the immune markers ARG1 and HLA-DQB2 and the tumour markers CDKN2A and KRT7, as possible markers for differentiating between CIN3 and normal tissue." (PMID 39712018, 2024). "As opposed to the conditioned medium from Sema3a deficient cells, the conditioned medium from SEMA3A expressing tumour cells significantly induced Arg1 expression without eliciting Nos2 expression." (PMID 38670629, 2024). "Mechanistically, p300-mediated acetylation of C/EBPβ leads to enhanced C/EBPβ transactivation activity on the Arg1 promoter subsequently enhancing Arg1 expression, and pharmacological inhibition of p300 led to reduced MDSC immunosuppressive activity and tumour burden in vivo." (PMID 38464388, 2024). "There were no changes in arginase-1 and CD11c protein levels in tumor lysates between HFD and HFD-IF." (PMID 38999849, 2024). "Indeed, Tregs inhibit the function of effector T cells and (NK) cells, while MDSCs suppress the function of immune cells by producing 1 (arginase 1 (ARG1)), which in turn favors tumor cell growth and inhibits immune cell function." (PMID 39195816, 2024). "In contrast to ARG1, NOS2 in macrophages is pro-inflammatory and tumor suppressive." (PMID 38422022, 2024). "In addition, it has been demonstrated that lactic acid, a byproduct of tumor cell glycolysis, acts as a potential signal triggering TAMs to adopt an M2 phenotype characterized by the expression of VEGF and Arginase-1, with HIF-1α facilitating this process." (PMID 38229178, 2024). "This induces IDO1 expression and leads to an immunosuppressive phenotype, and Arg1 and IDO1 may be closely related to tumor immunotherapy." (PMID 39144144, 2024). "Similarly, Smad4 deletion in S100A4+ cells down-regulated the expression of M1-like factors such as iNOS and IL-12 and up-regulated the expression of M2-related genes such as Arg1 and IL-10 in CRC tumor tissues." (PMID 39664586, 2024). "Consistent with the reduced population of CD206high TAMs, the amount of Arg1 mRNA was reduced in tumor tissues from mKO mice compared to WT mice, although we did not detect a difference in the mRNA expression of Nos2 in tumor tissues from these mice." (PMID 38308188, 2024). "This activation leads to metabolic reprogramming and increased activity of enzymes like glutaminase (GLS), indoleamine 2,3-dioxygenase (IDO), and arginase 1 (ARG1), depleting essential amino acids in the tumor microenvironment that are vital for effector immune cell function." (PMID 39664377, 2024). "Tumor-derived PGE2 suppresses the activation of DCs by reducing IL-12 production, inhibiting co-stimulation and upregulating programmed death-ligand 1 (PD-L1) and arginase 1 (Arg1)." (PMID 38927447, 2024). "M-MDSCs are abundant in tumour tissues, suppressing both an antigen-specific and non-specific T-cell response, mainly relying on arginase 1 (Arg1), nitric oxide (NO), and immunosuppressive cytokines." (PMID 38893071, 2024). "Tumor cell invasion was decreased in the presence CAF conditioned media (CM) depleted of DDR2 or arginase-1, and this invasion defect was rescued in the presence of CM from DDR2-depleted CAFs that constitutively overexpressed arginase-1." (PMID 37996700, 2024). "In contrast to classically activated Mφs that stimulate phagocytosis, inflammation, and host immunity, a prominent population of tumor Mφs undergo alternative, M2-like polarization to express anti-inflammatory molecules, such as IL-10, TGF-β, and arginase 1 to induce tumor immunosuppression." (PMID 38416830, 2024).
tumor (continued). "Activated ARG1 and nitric oxide synthase (NOS) in the tumor microenvironment affect TAMs and inhibit the production of nitric oxide (NO), which can promote the differentiation of M1 macrophages, thus facilitating tumor development." (PMID 39192979, 2024). "However, and quite paradoxically, it has been shown that ARG1 is decreased in HCC tumors whereas arginine level is increased and plays a major role in tumor formation." (PMID 39078527, 2024). "Indeed, lactate induces the release of VEGFA as well as arginase 1 (ARG1) and arginase 2 (ARG2), which dampen the activity of other immune cells and ultimately accelerate tumor progression." (PMID 38730724, 2024). "Relevant molecules in the tumor microenvironment including granulocyte colony-stimulating factor (G-CSF) and transforming growth factor-β (TGF-β) induce an increased secretion of ARG1, ROS, NO, PGE2 by neutrophils, thereby inhibiting the activation of CD8 + T cells and NK cells." (PMID 37644468, 2023). "Chronic inflammation is usually accompanied by the secretion of immunosuppressive factors such as ROS, ARG1, PGE2, PD-L1, IDO1, etc., resulting in promoting the formation of an inhibitory immune microenvironment and inhibiting tumor-killing effect of CD8+ T cells and NK cells." (PMID 37644468, 2023). "Our results showed that ARG1 protein was not expressed by cancer cells, but by cells with an appearance consistent with tumour-infiltrating immune cells." (PMID 37980483, 2023). "The AhR has been found to induce the expression of immunoregulatory enzymes and factors such as arginase 1 (Arg1], IDO, IL-10 and the S100 calcium binding protein S100A9 which are important for the immunosuppressive function of TAMCs by creating a tumor-promoting microenvironment." (PMID 37696458, 2023). "However, inhibiting ARG1/2 by OAT-1746 unlocks antitumor response in myeloid cells, T cells and NK cells, reduce the expression of tumor-supportive gene in TAMs, and improves the efficacy of the PD-1 checkpoint inhibition." (PMID 37598273, 2023). "Therefore, we assessed ARG1 protein expression in sorted CD45+ and CD45− cells from 67NR and 66cl4 tumours." (PMID 37980483, 2023). "Furthermore, ARG1- or ARG2-based vaccination in several murine models of cancer can activate specific T cells and induce tumor growth control." (PMID 36175673, 2023). "Interestingly, an opposite effect was observed in the hearts: the M1 marker decreased while the M2 markers (CD206, Arg1 and CD163) increased in TAC-operated, PyMT-bearing mice compared to non-tumor-bearing mice." (PMID 37508517, 2023). "By stabilizing HIF-1α, lactate could enhance VEGF and Arg1 expression and induces M2-like polarization of TAMs, and VEGF and Arg1 support tumor growth via inducing neovascularization and providing substrates for cancer cell proliferation, respectively." (PMID 37564659, 2023). "Immunohistochemical analysis revealed a significant increase in intratumoural infiltration of M1-like macrophages (iNOS+) at the expense of M2-like macrophages (Arg1/CD68+), and an increase in CD8 + T cells in Mettl1 +/- and Mettl1flox/flox tumours compared to Mettl1+/+ tumours." (PMID 37516825, 2023). "Among them, ARG1 and CPS1 genes exhibit the most significant down-regulation, whose log2 ratios by comparison between IHCC and non-tumor, as well as IHCC and normal bile duct, are −4.0505 and −2.9184 (p ≤ 0.0001) and −3.9435 and −2.8787 (p ≤ 0.0002), respectively." (PMID 37443694, 2023). "Thus, we compared the expression of arginase-1 (Arg1), one of the signature immunosuppression genes, in the sorted M-MDSC from naive spleen, spleen from tumor-bearing mice as well as from brain metastatic lesions." (PMID 37149684, 2023). "Furthermore, after L. casei & L. reuteri or TAK-242 treatment, the expressions of CD86 and iNOS were increased in tumor tissues, whereas the expressions of CD206 and Arg-1 were decreased at the same time." (PMID 37904102, 2023).
tumor (continued). "In addition, to obtain a more accurate conclusion, we also detected the expression of DNA‐PK and MDSCs functional markers (iNOS, Arg1, and IDO) in splenic MDSCs of tumor‐bearing mice treated with NU7441 in vivo." (PMID 36373232, 2023). "Whereas M2-like macrophages consumed arginine through arginase-1 to limit arginine accessibility to other anti-tumor immune cells such as Teff cells, which has a negative consequence on tumor killing." (PMID 37277776, 2023). "Our work provided new insights by showing that ARG1-positive myeloid cells were abundant in metastatic tumours and rare in non-metastatic ones." (PMID 37980483, 2023). "Using qRT-PCR and western blotting of tumour lysates, we confirmed elevated Arg1 mRNA and ARG1 protein levels in metastatic 66cl4 tumours compared to those in non-metastatic tumours." (PMID 37980483, 2023). "Also in these settings, the increased M2 phenotype triggered by the tumor cells was reverted upon SKI-II treatment, as evident by reduced expression of Arg1 and Msr1 and enhanced expression of Tnfα and Il-6." (PMID 36672428, 2023). "Normal breast fibroblasts did not significantly affect tumor angiogenesis or recruitment of arginase-1+ cells." (PMID 37091166, 2023). "Taken together, our results suggested that upregulation of CD40, CTLA4, ARG1, STAT3, IDO, and CD274, which were included in tumor inflammation signature, in the TME of KRASmut, could be characteristic of immune suppression." (PMID 36831441, 2023). "Immunohistochemically, the tumor cells are positive for Hep Par-1 and arginase-1 and negative for CK 19 and caudal-type homeobox 2 (CDX2)." (PMID 37761023, 2023). "Moreover, both TNC and CCL2 tumor levels correlated negatively with markers of M1 macrophage status (IL6) and positively with markers of M2 macrophage status (CD168 and Arg1), with a higher correlation of TNC than CCL2 at both 3 and 11 weeks." (PMID 37176074, 2023). "In HNSCC patients, Arg-1 mRNA expression in the tumor was reported to be a negative prognostic factor for overall survival." (PMID 38001706, 2023). "In 67NR tumours, only 3% of the Ly6G+ intermediate and negative subsets, and less than 1% of Ly6G+ high cells were ARG1 positive." (PMID 37980483, 2023). "Our results show, for the first time, that ARG1 is predominantly expressed by myeloid cells in metastatic tumour but not in non-metastatic ones." (PMID 37980483, 2023). "Furthermore, TAMs interact with various immune cells within the tumor microenvironment through other mechanisms, which include expression of Indoleamine 2,3-dioxygenase (IDO) and the production of Arg1, which is beyond the scope of the current analysis." (PMID 38012322, 2023). "For the macrophage subsets, treatment with CpG-2722 alone and combination of CpG-2722 and BPRDP056 promoted F4/80+ macrophage and iNOS+ M1 macrophage accumulation in tumors; conversely, no treatment affected the level of ARG-1 M2 macrophages in the tumor." (PMID 37324949, 2023). "Lower effects were obtained with HT29 M6 tumor cells expressing Snail1 that did not decrease macrophage cytotoxicity and only stimulated Arg1." (PMID 37199012, 2023). "Additionally, the expression levels of M2 markers such as CD206, ARG1, IL-10 and TGF-β were found to be upregulated, ultimately promoting CRC tumor progression and metastasis." (PMID 37943609, 2023). "Mechanistically, HOTAIRM1 could impair the antitumor immune response by MDSCs and delay tumor progression though increasing the expression of HOXA1 in MDSCs, which promotes Arg1 secretion." (PMID 37637063, 2023). "We analyzed via qPCR the expression level of anti-inflammatory (M2) genes in the microglia and showed that, in these co-culture settings, microglia presented an increased expression of the M2 marker Arg1 compared with cells cultured in the absence of tumor." (PMID 36672428, 2023). "Arg-1 plasma levels did not correlate with the tumor clinicopathological features, such as tumor differentiation, nodal involvement and tumor recurrence." (PMID 38001706, 2023).
tumor (continued). "Arginase 1 (ARG1) gene and protein was highly expressed in myeloid cells of metastatic tumours, while it was nearly absent in these cells originating from non-metastatic ones." (PMID 37980483, 2023). "The as-synthesized Fe-CDs could selectively induce tumor cells apoptosis by BAX/Caspase 9/Caspase 3/PARP signal pathways and activate antitumoral macrophages by inhibiting the IL-10/Arg-1 axis, contributing to its significant tumor immunotherapy effect." (PMID 37978538, 2023). "In addition, olaparib at sub-IC50 concentrations can block the expression of ARG-1, iNOS, and COX-2 and reduce the inhibitory function of MDSC, which is more effective in blocking tumor progression when used in conjunction with anti-PD-1." (PMID 37415162, 2023). "Furthermore, we found that NU7441 increased the mRNA expression of DNA‐PK and functional markers of MDSCs (iNOS, Arg1, IDO) in the splenic MDSCs of tumor‐bearing mice both in vivo and in vitro." (PMID 36373232, 2023). "Inhibition of Arg-1 and iNOS expression inhibits polyamine production and the TCA cycle, thereby further suppressing the immunosuppressive capacity of PMN-MDSCs and enhancing the antitumor effects of anti-PD1 mAb therapy in B16-F10 and 4 T1 mouse tumor models." (PMID 36854755, 2023). "Dual-color IF staining showed that blocking eIF5Ahpu by GC-7 treatment reduced tumor infiltration of total F4/80+ macrophages and the proportion of F4/80+/CD206+ macrophages as well as CD206+/ARG1+ and CD206+/HO-1+ M2-like macrophages in tumor microenvironment." (PMID 37653021, 2023). "DCIS fibroblasts significantly enhanced recruitment of arginase-1+ cells but did not significantly affect tumor angiogenesis as indicated by VWF8 expression, compared to DCIS.com cells alone and normal breast fibroblasts." (PMID 37091166, 2023). "In contrast to its strong inhibition of poly(I:C)-engaged Arg1 expression, U0126 did not significantly alter the whole-tumor expression patterns of Emr1 and Ly6c1, markers respectively associated with macrophages and monocytes." (PMID 36726024, 2023). "These genes include markers of alternative macrophage polarization (Arg1, Cd163), monocyte chemoattractant Ccl6, and ligands for CCR2 (Ccl2, Ccl7, Ccl12) and CCR5/1 (Ccl3, CCl4, Ccl9) suggesting that F4/80+ cells in these tumours represent an increase in TAM2‐like myeloid cells." (PMID 35924447, 2023). "The results showed that the expression of the immunosuppressive genes Arg1 and TGFβ in bone marrow G-MDSCs did not change with tumor progression." (PMID 35013108, 2022). "They found that dendrosomal curcumin increases the gene expression of STAT4 and IL-12 in tumor and spleen tissues, probably reflecting the high levels of M1 macrophages, and decreases the gene expression of STAT3, IL-10, and arginase-1, indicating low levels of M2 macrophages." (PMID 36142391, 2022). "This reduction in intracellular cholesterol enhances IL-4 receptor (IL-4R)/STAT6/PI3K signaling in vitro and in vivo, promoting the expression of the typical M2 marker arginase-1 while inhibiting NOS2 and proinflammatory IL-12 expression, thereby promoting tumor progression." (PMID 34876704, 2022). "M2 GAMs further produce more Arg-1, TGF-β, IL-10, IL-6, and other abundant immunosuppressive cytokines, thus foster immunosuppression and pro-angiogenesis which contribute to growth and invasion of GBM after GBM tumor cells adapt to the pro-inflammatory TME." (PMID 35572545, 2022). "MDSC and tumor-promoting neutrophils clearly differentiate into divergent cell types, as MDSCs have reduced expression of CD16 and CD62L and increased expression of Arg-1, CD66B, and CD11b." (PMID 35267547, 2022). "The nature of immune suppression by MDSCs is to hamper the recognition of tumor cells by cytotoxic T lymphocytes in non-specific ways through ROS, Arg-1, NO, and peroxynitrite (PNT), and in an antigen-specific way." (PMID 35267547, 2022).